CTNS (cystinosin, lysosomal cystine transporter)
Diseases named in the same sentence as CTNS in open-access papers (continued):
Sharing a sentence is not in itself a finding about the gene and the disease.
lysosomal storage disease (34 papers, 2015 to 2026). A metabolic disorder caused by mutations in proteins critical for lysosomal function, including lysosomal enzymes, lysosomal integral membrane proteins, and proteins involved in the post-translational modification and trafficking of lysosomal proteins. "Nephropathic cystinosis is a lysosomal storage disease due to biallelic pathogenic variants in the CTNS gene encoding the cystine transport protein cystinosin." (PMID 40369127, 2026). "Cystinosis is a systemic lysosomal storage disease resulting from mutations in the CTNS gene encoding the lysosomal cystine transporter cystinosin, leading to cystine accumulation in all organs." (PMID 41876818, 2026). "Cystinosis is an autosomal recessive lysosomal storage disorder caused by mutations in the CTNS gene which encodes for the cystine transporter protein, cystinosin." (PMID 39990449, 2025). "Cystinosis is a rare lysosomal storage disorder caused by autosomal recessive mutations in the CTNS gene that encodes for the cystine transporter cystinosin, which is expressed on the lysosomal membrane mediating the efflux of cystine." (PMID 38794219, 2024). "Cystinosis—one of a family of approximately 70 rare inborn diseases of the metabolism known as lysosomal storage diseases —is caused by inactivating mutations in the CTNS gene encoding the proton-driven transporter cystinosin, which exports cystine from the endolysosome." (PMID 35159136, 2022).
nephropathic cystinosis (28 papers, 2006 to 2025). An autosomal recessive condition caused by mutation(s) in the CTNS gene, encoding cystinosin. "Nephropathic cystinosis is an autosomal recessive chronic kidney disease condition caused by mutations in the CTNS gene." (PMID 35011739, 2022). "The aim of this study was to analyze the CTNS mutations in 20 Iranian patients, from 20 unrelated families, all of whom were afflicted with infantile nephropathic cystinosis." (PMID 28983406, 2017). "Nephropathic cystinosis (MIM 219800) is an autosomal recessive disorder caused by mutations in the CTNS gene encoding cystinosin, a lysosomal cystine transporter." (PMID 25811383, 2015). "The CTNS gene mutation causes infantile nephropathic cystinosis (INC)." (PMID 39210624, 2024). "Nephropathic cystinosis is a rare and severe disease caused by disruptions in the CTNS gene." (PMID 35011739, 2022). "Infantile nephropathic cystinosis (INC) is a rare autosomal recessive storage disease, due to mutations in the CTNS gene encoding for the lysosomal cystine transporter cystinosin." (PMID 35011732, 2022). "Infantile nephropathic cystinosis (INC), a genetic chronic kidney disease (CKD), results from cystinosin (CTNS) mutations and involves the deposition of cystine crystals in multiple organs." (PMID 36291130, 2022). "Based on the identified aberration of CTNS mRNA sequence we detected a novel 9-kb homozygous deletion in the CTNS gene and confirmed the molecular diagnosis of infantile nephropathic cystinosis in this patient." (PMID 31672123, 2019).
myocardial infarction (10 papers, 2016 to 2024). Gross necrosis of the myocardium, as a result of interruption of the blood supply to the area, as in coronary thrombosis. "In general population cohorts, differences in associations with outcomes have been reported for low-grade elevations of hs-cTns: cTnI was associated with myocardial infarction (MI) and elevated cTnT was more strongly associated with all-cause mortality and non-CV death." (PMID 38410245, 2024). "The introduction of high-sensitivity cardiac troponin (hs-cTn) assays has revolutionized the clinical utility of cTns, moving beyond their traditional role as a dichotomous marker for acute myocardial infarction (MI)." (PMID 39610975, 2024). "After myocardial infarction, intracellular proteins from dying cardiomyocytes are released into the bloodstream, and several proteins (e.g., myosin light chains and cTns) can be identified in the blood of patients with myocardial infarction." (PMID 38542091, 2024). "The purpose of this comprehensive review is to systematize information about the metabolism of cardiac troponins and during the discussion to focus on the potential impact of cTns metabolism on the laboratory diagnosis of myocardial infarction." (PMID 35402607, 2022). "Cardiac troponins (cTns) have long been the most valuable and specific biomarkers for detecting ischemic myocardial cells (MCs) injury, which is one of the key signs of myocardial infarction (MI)." (PMID 35723315, 2022). "This will allow doctors and researchers to understand the significant importance of cTns metabolism and its impact on the laboratory diagnosis of myocardial infarction." (PMID 35402607, 2022). "This advancement leads to a more general leveraging of cTns assay; they have been introduced into the diagnostics of early acute myocardial infarction and chronic cardiomyopathies that are accompanied by milder plasma cTns level elevations." (PMID 32674303, 2020). "The use of miRNAs against traditional biomarkers for different diseases is being explored, such as circulating troponins (cTns) for the diagnosis of acute myocardial infarction (MI)." (PMID 38003397, 2023). "Cardiac troponins (cTns) (cTnI and cTnT) have long been the most valuable and specific biomarkers for detecting ischemic myocardial cells (MCs) injury, which is one of the key signs of myocardial infarction (MI)." (PMID 35723315, 2022).
Fanconi syndrome (7 papers, 2011 to 2025). "CTNS−/− knockout mice do not develop overt Fanconi syndrome for, so far, unknown reasons." (PMID 35011732, 2022).
chronic kidney disease (6 papers, 2016 to 2024). Impairment of the renal function secondary to chronic kidney damage persisting for three or more months. "Furthermore, in conditions of chronic renal failure, the expression of cTns in skeletal muscles is noted, which, according to some authors, can lead to an increase in the serum concentrations of cTns in patients with chronic renal failure." (PMID 35336802, 2022).
renal Fanconi syndrome (6 papers, 2017 to 2025). "Amongst these long-term consequences are renal Fanconi syndrome, hypophosphatemic rickets, malnutrition, hormonal abnormalities, muscular impairment, and intrinsic cellular bone defects in bone cells, due to CTNS mutations." (PMID 35011732, 2022). "While CTNS is ubiquitously expressed and cystine accumulates in all tissues, the kidney is the primary organ affected which shows the earliest manifestation of the disease phenotype with renal Fanconi syndrome (FS) at 6–18 months of age." (PMID 39990449, 2025). "In order to rule out monogenic forms of renal Fanconi syndrome, molecular genetic screening for variants in CLCN5, OCRL1 and CTNS was initially performed in Patient 1 (P1)." (PMID 31435670, 2019).
Sepsis (3 papers, 2019 to 2022). Sepsis is defined as life-threatening organ dysfunction caused by a dysregulated host response to infection. "In other pathological conditions that are accompanied by the inhibition of the filtration rate, for example, in sepsis, serum levels of cTns are positively correlated with serum creatinine levels, which also accumulate due to a decrease in the filtration capacity of nephrons." (PMID 35336802, 2022). "Thus, in minor or reversible (short-term) ischemia that develops during physical exercise and psychoemotional stress, the extent of cTns increase is less significant than in sepsis or MI." (PMID 35723315, 2022). "In pathological conditions that cause the irreversible ischemia of MCs (for example, MI or severe/complicated sepsis), serum troponin levels increase much more significantly, and the main contribution to total serum levels of cTns will be made by the structural fraction of cTns." (PMID 35336802, 2022).
breast carcinoma (2 papers, 2024). "Increased lysosomal stores of cyst(e)ine, which is released by cystinosin (CTNS) to maintain GSH levels and buffer oxidative stress in breast cancer cells, occurs through activation of the major facilitator superfamily domain containing 12 (MFSD12)." (PMID 38785550, 2024).
COVID-19 (2 papers, 2022). A disease caused by infection with severe acute respiratory syndrome coronavirus 2. "Previous studies have found an increase in cardiac troponins (cTns) and echocardiographic abnormalities in patients with COVID-19 and reported their association with poor clinical outcomes." (PMID 35727386, 2022). "The dose–response analysis showed that for every 1 × 99th percentile URL increment in cTns elevation, the pooled OR was 1.23(95% CI 1.20–1.26, P = 0.000) for the risk of short-term all-cause mortality in patients with COVID-19." (PMID 35586652, 2022). "In this dose–response meta-analysis of retrospective studies, we found that myocardial injury as defined by elevated cTns above the 99th percentile URL was associated with a 3.17-fold increased risk of short-term mortality in patients with COVID-19." (PMID 35586652, 2022). "Pubmed, Embase, and the Cochrane Library database were searched for all the studies which evaluated the relationship between cTns and the risk of short-term all-cause mortality in patients with COVID-19." (PMID 35586652, 2022). "Our meta-analysis suggested that routine screening cTns at admission would be helpful for risk-stratification and guide further management for patients with COVID-19." (PMID 35586652, 2022). "The dose–response analysis showed that for every 1x99th percentile URL increment in cTns elevation, the pooled OR was 1.25 (95% CI 1.22–1.28, P = 0.000) for the risk of all-cause mortality in patients with COVID-19." (PMID 35586652, 2022). "However, we performed sensitivity analysis restricted to the studies with multi-variable adjusted and found that there was also a positive dose–response relationship between cTns and short-term death in patients with COVID-19." (PMID 35586652, 2022). "Predictive value of myocardial injury as defined by elevated cardiac tropnins (cTns) in patients with COVID-19 has not been fully investigated." (PMID 35586652, 2022).
diabetes (2 papers, 2018 to 2022). "For example, several pilot studies have clearly demonstrated the diagnostic value of hs-cTns in oral fluid in case of MI, in urine in case of diabetes mellitus (DM), and in urine in case of arterial hypertension (AH)." (PMID 35723315, 2022).
ischemia (2 papers, 2022). A hypoperfusion of the BLOOD through an organ or tissue caused by a PATHOLOGIC CONSTRICTION or obstruction of its BLOOD VESSELS, or an absence of BLOOD CIRCULATION. "A possible mechanism underlying the release of cTns is small-scale necrotic processes, which can be caused by both ischemia and inflammatory-toxic processes, imbalances in the neurohumoral system." (PMID 35336802, 2022). "Based on the peculiarities of the formation of blebbing vesicles (a significant increase in ischemia), it can be assumed that this mechanism is involved in the release of cTns in those pathological conditions that are accompanied by the ischemia of MCs at an early stage." (PMID 35336802, 2022). "Thus, elevated cTns levels may indicate the diagnosis of MI only if there are any clinical signs of myocardial ischemia and typical myocardial ischemic changes of ECG, whereas without signs of ischemia cTns merely indicate the presence of MCs injury." (PMID 35723315, 2022).
kidney failure (2 papers, 2022 to 2025). An acute or chronic condition that is characterized by the inability of the kidneys to adequately filter the blood. "Kidney failure arising from renal proximal tubule dysfunction represents the most severe phenotype arising in humans with loss-of-function mutations in CTNS." (PMID 40661466, 2025). "Renal failure can be noted as an example of a significant factor affecting the removal of cTns from the bloodstream." (PMID 35336802, 2022). "However, in these studies, the authors did not measure the serum levels of cTns in patients with myopathies and renal failure." (PMID 35336802, 2022).
myocardial ischemia (2 papers, 2022). A disorder of cardiac function caused by insufficient blood flow to the muscle tissue of the heart. "Therefore, cTn molecules were considered as strictly intracellular molecules and the presence of cTns in blood serum was considered as one of the key pathological criteria to confirm MI in patients with clinical signs of myocardial ischemia." (PMID 35723315, 2022). "For example, the initial (prenecrotic) stage of myocardial ischemia can provoke the formation of blebbing vesicles, and the release of cTns into the bloodstream, which will lead to the formation of the first peak in serum concentrations of cTns." (PMID 35336802, 2022). "If elevated serum levels of cTns are combined with signs of myocardial ischemia, then this is a MI." (PMID 35723315, 2022). "So, if serum levels of cTns are elevated, but there are no signs of myocardial ischemia, then this is myocardial injury." (PMID 35723315, 2022).
myocarditis (2 papers, 2024 to 2026). Myocarditis is a condition that is characterized by inflammation of the heart muscle (myocardium). "Rising CK levels that predate elevations in cTns in ICI-myocarditis have been noted, although CK and CK-MB are generally less sensitive and specific for myocardial injury." (PMID 38410245, 2024). "Cardiac troponins (cTns) are an essential component of the diagnosis of ICI-myocarditis, and we provide a summary of the recent studies that utilized different assays (cTnI vs. cTnT) and outcomes (diagnosis vs. prognosis including major adverse cardiac outcomes)." (PMID 38410245, 2024). "Currently recommended initial tests in patients with suspected ICI-myocarditis include electrocardiography (ECG), cardiac troponins (cTns), natriuretic peptides (NPs), and echocardiography." (PMID 38410245, 2024). "Preliminary clinical observations further suggest that H-FABP elevations may occur during ICI treatment even in the absence of overt myocarditis or concomitant increases in high-sensitivity cardiac troponins (hs-cTns)." (PMID 42278370, 2026).
Obesity (2 papers, 2021 to 2024). Accumulation of substantial excess body fat. "In our study, hs-cTns were significantly related to age > 40 years, obesity, decreased eGFR and increased BNP." (PMID 39685587, 2024). "The use of these biomarkers (NPs, cTns) in the older population may be limited, since their levels are influenced by age, obesity and kidney function." (PMID 33799487, 2021).
pulmonary embolism (2 papers, 2016 to 2022). The obstruction of the pulmonary artery or one of its branches by an embolus, sometimes associated with infarction of the lung. "However, for example, on high-intensity exertion, or in massive pulmonary embolism, myocardial overload becomes much more significant, and therefore, these conditions are accompanied by relatively higher serum levels of cTns." (PMID 35336802, 2022). "It is also important to investigate whether exosomes are elevated in the blood early after a MI and in other ischemic conditions resulting in high cTns level, such as pulmonary embolism and pulmonary arterial hypertension." (PMID 27128471, 2016). "For example, relatively small myocardial overload is observed on mild to moderate exertion, in hypertension and non-massive pulmonary embolism, so the increase in serum levels of cTns in these conditions is also relatively small." (PMID 35336802, 2022).
acute coronary syndrome (1 paper, 2019). Signs and symptoms related to acute ischemia of the myocardium secondary to coronary artery disease. "More specifically, molecular imprinting is critically evaluated with respect to the detection of cardiac biomarkers indicative of acute coronary syndrome (ACS), such as the cardiac troponins (cTns)." (PMID 31395843, 2019).
Anxiety (1 paper, 2017). Intense feelings of nervousness, tension, or panic often arise in response to interpersonal stresses. "The relationship between depression/anxiety severity and genes expression profiles (STRN, CD84 and CTNS) in SSD patients." (PMID 28333931, 2017). "The relationship between depression/anxiety severity and genes expression profiles (STRN, CD84 and CTNS) in MDD patients." (PMID 28333931, 2017).
cardiotoxicity (1 paper, 2025). Toxicity that impairs or damages the heart. "Elevated baseline levels of hs-cTns may suggest chemotherapy-vulnerable myocardium, as evidenced by the observation that they can predict future anthracycline-induced decline in LVEF and even cardiotoxicity." (PMID 41303748, 2025).
cystic fibrosis (1 paper, 2024). Autosomal recessive disorder caused by pathogenic variants in the CFTR gene (cystic fibrosis transmembrane conductance regulator), which encodes a chloride and bicarbonate channel expressed in epithelial cells, and follow the diagnosis criteria. "Taken together, our study underscores that there is a need for a more nuanced interpretation of CTNS mutations, revealing variable cystine transport activity for different CTNS mutations, similar to observations in cystic-fibrosis-associated CFTR mutations." (PMID 38607085, 2024).
Immunodeficiency (1 paper, 2006). Failure of the immune system to protect the body adequately from infection, due to the absence or insufficiency of some component process or substance. "Underexpressed SDHD and CTNS are associated with immunodeficiency through curbed monocyte and CD4+ T cell -induced immunoregulation, respectively." (PMID 16956415, 2006).
injury (1 paper, 2022). Damage inflicted on the body as the direct or indirect result of an external force, with or without disruption of structural continuity. "Compared with patients without myocardial injury, the group with elevated cTns was associated with increased short-term mortality (11 studies, 29,128 subjects, OR 3.17, 95% CI 2.19–4.59, P = 0.000, I2 = 92.4%, P for heterogeneity 0.00)." (PMID 35586652, 2022).
melanoma (1 paper, 2016). A malignant, usually aggressive tumor composed of atypical, neoplastic melanocytes. "Recently, cystinosin was implicated in the regulation of melanin synthesis as CTNS silencing in a melanoma cell model led to over 50 % reduction in pigment production." (PMID 27102039, 2016).
Myocardial fibrosis (1 paper, 2021). "Finally, in non-high-risk HCM patients, cTns haven been shown to be indicative of myocardial fibrosis and can therefore be used to select patients for CMR with LGE or T1 mapping." (PMID 33799487, 2021).
pulmonary edema (1 paper, 2022). Accumulation of fluid in the lung tissues causing disturbance of the gas exchange that may lead to respiratory failure. "We have selected extremely high-risk patients with quite elevated level of pro Bnp > 1000 and we further stratify them using Hs-cTns and radiological evidence of pulmonary edema, both biomarkers are measured in the laboratories and their blood levels are pathophysiologically explained." (PMID 35115590, 2022).
rickets (1 paper, 2019). Bone softening and weakening usually caused by deficiency or impaired metabolism of vitamin D. Deficiency of calcium, magnesium, or phosphorus may also cause rickets. "Mutations in the human cystinosin gene CTNS lead to cystinosis, a disease characterized by rickets, renal failure, growth retardation, and eventually death." (PMID 31100816, 2019).
skeletal myopathies (1 paper, 2022). "This is an important limitation of these studies because it does not answer the question: can the expression of cTns in skeletal muscles lead to an increase in the serum levels of cTns in patients with CRF or hereditary skeletal myopathies?" (PMID 35336802, 2022).